RIPK1 (receptor interacting serine/threonine kinase 1)
Diseases named in the same sentence as RIPK1 in open-access papers (continued):
Sharing a sentence is not in itself a finding about the gene and the disease.
Arthritis (16 papers, 2018 to 2025). Inflammation of a joint. "Clinical studies have reported that mutations in the RIPK1 gene lead to its loss of function, which causes a variety of autoimmune inflammation conditions in patients, including arthritis." (PMID 36993980, 2023). "Loss of function mutations preventing kinase activity of RIPK1 itself as well as heterozygous Casp8 cleavage-site mutations allowing unregulated activity of RIPK1 cause severe primary immunodeficiency, intestinal inflammation, arthritis, and CRIA in humans." (PMID 37965338, 2023). "Alternatively, RIPK1 inhibition in a murine collagen-induced arthritis model was able to reduce proinflammatory cytokine expression of IL-17, IL-1β, IL-6, and TNFα, suggesting that RIPK1 inhibition has the potential to impact myeloid and T cell responses." (PMID 41019071, 2025). "Mechanistically, RIPK1 biallelic variants can impair RIPK1 ubiquitination leading to the loss of RIPK1 protein expression, which can ultimately suppress the formation of the TNFR1 signaling complex and reduced NF-κB activation, resulting in arthritis." (PMID 41019071, 2025). "It is important to note that the responses observed in murine models seldom mirror clinical outcomes, especially since the induction of arthritis in the murine model does not accurately recapitulate genetic abnormalities associated with RIPK1 in humans." (PMID 41019071, 2025). "Similarly to previous reports of RIPK1 deficiency, the patients all presented with diarrhea and growth failure secondary to IBD and 3 of them also developed recurrent infections and arthritis by the time they were referred to a transplant center." (PMID 39762600, 2025). "Collectively, our results show that SF-Cyld controls TAK1 kinase to prevent IKK2 and NF-κB hyperactivation but not Ripk1-mediated death, leading to deterioration of arthritic phenotype in TNF-dependent arthritis." (PMID 39122678, 2024).
Cerebral ischemia (16 papers, 2018 to 2025). Restriction of arterial blood supply to the brain associated with insufficient oxygenation to support the metabolic requirements of the tissue. "This argues for a critical role of ASIC1a in bridging the association between NSF and RIPK1 in response to brain ischemia." (PMID 31980622, 2020). "Elevated expression of necroptotic RIPK1 has been implicated in cerebral ischemia brain injury." (PMID 34943061, 2021). "In the study of cerebral ischemia models, it was found that the degree of brain injury and neuronal death decreases when the phosphorylation of RIPK1/3 protein is inhibited." (PMID 39657719, 2024). "To confirm the data obtained in vitro, we studied the effect of RIPK1 blockade on the resistance of small laboratory animals to in vivo modeling of hypoxia and cerebral ischemia." (PMID 35054920, 2022). "We found that cerebral ischemia stimulated phosphorylation of RIPK1 at the Ser166 residue and increased RIPK3 and MLKL expression levels in the brain." (PMID 31440386, 2019). "Due to the specific activation of p-RIPK1 (Ser166) in cerebral ischemia, we suggest further studies to explore its feasibility as a biomarker for necroptosis and a potential therapeutic target for neuroprotection." (PMID 31440386, 2019). "Furthermore, NDRG2 has been shown to repress the function of receptor interacting protein kinase 1 (RIPK1), consequently ameliorating astrocyte necrosis post-cerebral ischemia." (PMID 38419793, 2024). "In contrast with wild‐type mice, RIPK1 kinase‐dead mice, RIPK3 deficient mice, and MLKL deficient mice showed reduced levels of cell necrosis and neuroinflammation after cerebral ischemia, which is highly consistent with the apoptotic pathway of necrotic cells." (PMID 39657719, 2024). "Our data suggest that (i) p-RIPK1 (Ser166) participated in RIPK3/MLKL-dependent neuronal necroptosis after cerebral ischemia; (ii) immunostaining with a specific antibody against p-RIPK1 (Ser166) could be used as a morphological biomarker for necroptosis." (PMID 31440386, 2019). "Moreover, both in vitro models of oxidative stress and in vivo models of cerebral ischemia have shown pharmacological inhibition of RIPK1 with Necrostatin-1 (Nec-1) significantly attenuates neuronal necroptosis, supporting its therapeutic potential in reducing neuroinflammatory damage." (PMID 41019071, 2025). "Similarly, in murine models of cerebral ischemia, RIPK1 activation in microglia and astrocytes leads to the release of proinflammatory cytokines and lysosomal dysfunction, respectively, while in neurons and oligodendrocytes, RIPK1 activation contributes to cell death." (PMID 41019071, 2025). "The expression of necroptosis kinases, including MLKL/p-MLKL, RIPK3/p-RIPK3, and RIPK1/p-RIPK1, was significantly increased in the brain tissue of an OGD-induced neuronal injury model and the brain tissue of cerebral ischemia animal models." (PMID 40636901, 2025). "Additionally, BCP has been observed to attenuate neuronal necrosis and the expression of receptor-interaction protein kinase-1 (RIPK1), receptor-interaction protein kinase-3 (RIPK3) and mixed-lineage kinase domain-like protein (MLKL) in cerebral ischemia." (PMID 38542177, 2024). "Oxygen-glucose deprivation (OGD), an in vitro model of cerebral ischemia, can also induce the death receptor (DR)-dependent component of necroptotic cell death in cultured neurons, concomitant with the increase in RIPK3/RIPK1 mRNA and protein levels." (PMID 29686306, 2018).
multiple sclerosis (16 papers, 2017 to 2024). A progressive autoimmune disorder affecting the central nervous system resulting in demyelination. "Receptor interacting serine/threonine protein kinase 1 (RIPK1) activation and necroptosis have been genetically and mechanistically linked with human multiple sclerosis and neurodegenerative diseases for which demyelination is a common key pathology." (PMID 35365618, 2022). "They demonstrate detrimental non-cell-autonomous consequences on oligodendrocytes and use animal models and human tissue to establish the involvement of RIPK1 in progressive forms of multiple sclerosis." (PMID 33979622, 2021). "Receptor interacting protein kinase 1 (RIPK1) mediates cell death and inflammatory signaling and is increased in multiple sclerosis (MS) brain samples." (PMID 33979622, 2021). "For noninfectious diseases, inhibition of the RIPK1-dependent necroptosis pathway can ameliorate ischemia-reperfusion injury in the brain, kidney, and heart and alleviate retinal degeneration, brain impact trauma, ethanol-induced liver injury, multiple sclerosis, and tumor progression." (PMID 34745415, 2021).
dermatitis (15 papers, 2014 to 2025). An inflammatory process affecting the skin. "Ablation of RIPK3 in these KC-selective RIPK1-deficient mice averts skin inflammation, indicating the high potency of necroptosis in driving dermatitis." (PMID 38649745, 2024). "Our study supports this paradigm, as in addition to preventing RIPK1 deficiency-caused spontaneous skin inflammation, keratinocyte-specific MLKL deficiency also prevented exogenous disturbance-induced skin inflammation." (PMID 36344541, 2022). "Surprisingly, genetic ablation of the kinase activity of RIPK1 was substantially less effective than loss of TNFR1 in preventing dermatitis as Ripk1D138N;HoipE-KO mice died at around P8 from severe skin disease." (PMID 30254289, 2018). "Genetic ablation of key apoptotic mediators, such as caspase-8, FADD and RIPK1, in mouse KCs triggers KC necroptosis and severe skin inflammation." (PMID 38649745, 2024). "Here we show that ZBP1 causes skin inflammation by inducing RIPK3-mediated necroptosis and RIPK1-caspase-8-mediated apoptosis in keratinocytes." (PMID 38849574, 2024). "ΔKerOTULIN mice are fully protected from dermatitis and skin tumorigenesis when crossed to a TNFR1-deficient or RIPK1 kinase-mutant background." (PMID 34625556, 2021). "Mirroring genetic studies, small-molecule RIPK1 inhibitor GNE684 therapy in Sharpincpdm/cpdm mice with established dermatitis reduced inflammation and caspase-3 cleavage in the skin." (PMID 33924766, 2021). "Strikingly, pharmacologic inhibition of the kinase activity of RIPK1 rescued the majority of Tnfr1KO;Hoil-1E-KO mice from dermatitis for the duration of the treatment with only three of the ten treated mice developing small punctate scales." (PMID 30254289, 2018). "We provide genetic and pharmacological evidence that the postnatal lethal dermatitis in HoipE-KO and Hoil-1E-KO mice is caused by TNFR1-induced, caspase-8-mediated apoptosis that occurs independently of the kinase activity of RIPK1." (PMID 30254289, 2018). "Nonetheless, the combination of the inhibition of RIPK3-MLKL-dependent necroptosis and RIPK1-caspase-8-driven cell death could fully prevent skin inflammation mediated by ZBP1ca." (PMID 40006996, 2025). "Mice with epidermal keratinocyte-specific ablation of RIPK1 (RIPK1E-KO) develop severe skin inflammation mediated by RIPK3-MLKL-dependent keratinocyte necroptosis, which is strongly suppressed by ZBP1 deficiency but only partially ameliorated by TNFR1 knockout." (PMID 38849574, 2024). "Histological analysis from five months old Tank/Azi2DKO/Ripk1KD/KD mice revealed that the skin inflammation was fully rescued by ablation of RIPK1 kinase activity, and we observed typical deposition of subdermal fat that was not distinguishable from control Azi2−/−/Ripk1KD/KD animals." (PMID 39562788, 2024). "Therefore, inhibition of RHIM-dependent RIPK1 signaling prevented MLKL-independent skin inflammation induced by ZBP1ca expression in keratinocytes." (PMID 38849574, 2024). "Importantly, ZBP1ca induced caspase-8-mediated skin inflammation by RHIM-dependent but kinase activity-independent RIPK1 signaling." (PMID 38849574, 2024). "Overall, the complexity of RIPK1’s role in skin inflammation suggests that caution should be taken when targeting RIPK1 in all hyperinflammatory disorders, or that rationally designed drugs targeting other cell death machinery may have merit." (PMID 33924766, 2021). "Genetic deletion of Tnfr1, knockin expression of kinase-inactive Ripk1 or keratinocyte-specific deletion of Fadd and Mlkl completely rescues mice with OTULIN deficiency from dermatitis and tumorigenesis, thereby identifying keratinocyte cell death as the driving force for inflammation." (PMID 34625556, 2021). "Furthermore, a K45A knock-in mutation of Ripk1 that disables its kinase activity (and thus RIPK1-dependent death) also reversed the skin inflammation in the cpdm mice." (PMID 31457011, 2019).
dermatitis (continued). "Thus the lethal dermatitis caused by keratinocyte-specific HOIL-1 that occurs in the absence of TNFR1 is mediated by RIPK1 kinase-dependent apoptosis and necroptosis." (PMID 30254289, 2018). "Our previous studies identified ZBP1 as a potent driver of keratinocyte necroptosis and skin inflammation in mice lacking RIPK1 in keratinocytes or expressing RIPK1 with mutated RHIM, suggesting that ZBP1 could be implicated in inducing keratinocyte necroptosis in FADDE-KO mice." (PMID 38849574, 2024). "Dermatitis in Sharpincpdm/cpdm mice is driven by TNF/TNFR signalling in keratinocytes and is dependent on the kinase activity of RIPK1, and also partly dependent on NLRP3 inflammasome-mediated IL-1β activity and IL-1 receptor signalling." (PMID 33924766, 2021). "Moreover, the skin inflammation in these mice was driven by TNF, epithelial TNFR1 and RIPK1 kinases, FADD/ caspase-8-mediated cell death, and innate immune sensors, adaptors and components of inflammasomes." (PMID 40006996, 2025). "In conclusion, we could demonstrate that dermatitis and tumor development in ΔKerOTULIN mice depends on the cytotoxic activity of TNF driving FADD- and RIPK1 kinase-dependent death of keratinocytes." (PMID 34625556, 2021). "In the absence of TNFR1, however, dermatitis develops in adulthood, triggered by RIPK1-kinase-activity-dependent apoptosis and necroptosis." (PMID 30254289, 2018). "Our findings that inhibition of RHIM-dependent RIPK3 signaling did not fully prevent skin inflammation in ZBP1caE-het mice suggested that ZBP1ca could induce keratinocyte cell death by activating RIPK1." (PMID 38849574, 2024). "Curiously, while inhibition of the kinase activity of RIPK1 restores viability of HOIP-deficient PMKs in vitro, neither pharmacologic inhibition nor genetic impairment of RIPK1’s kinase activity in HoipE-KO mice prevented keratinocyte death and consequent dermatitis." (PMID 30254289, 2018). "Furthermore, these results indicate that the suppression of cpdm dermatitis seen by crossing to mice lacking RIPK1 kinase activity may, surprisingly, be due to RIPK1’s kinase activity being upstream of caspase-8 in mediating TNF-induced apoptosis." (PMID 25443632, 2014). "Absence of the RIPK1 RHIM domain in KCs leads to spontaneous Z-DNA-binding protein 1 (ZBP1)-dependent necroptosis, severe skin inflammation and perinatal lethality." (PMID 38649745, 2024). "Thus lethal dermatitis caused by keratinocyte-specific deficiency in either HOIP or HOIL-1, the two essential components of LUBAC28, is only partially dependent on TNFR1 and, in the presence of TNFR1, almost completely independent of the kinase activity of RIPK1." (PMID 30254289, 2018). "This indicates that augmented cell death in the absence of Mib2 was not occurring in the skin of SharpincpdmMib2−/− mice and, therefore, in this context MIB2 deletion does not restrain dermatitis in Sharpincpdm animals by inhibiting TNF-induced and RIPK1-mediated cell death." (PMID 38156288, 2024).
ischemic stroke (15 papers, 2019 to 2026). A stroke disorder caused by obstruction of blood flow to the brain, due to thrombotic (local blood clot formation) or embolic (due to a blood clot or other material traveling from another site) event. "Because ASIC1a signaling and RIPK1-dependent cell death had so far only been linked to ischemic stroke, future studies should investigate the potential role of ASIC1a as an upstream target for inducing RIPK1-dependent cell death in other CNS diseases." (PMID 35961983, 2022). "The simultaneous knockdown of Ripk1 and Nsf exerts its effects on ischemic stroke through the RIPK1/RIPK3/ mixed lineage kinase domain-like protein (MLKL) signaling pathway involved in necroptosis." (PMID 38919602, 2024). "Recently studies have identified ASIC1a as a new death receptor that recruits RIPK1 to its C-terminus, leading to the phosphorylation of RIPK1 and subsequent neuronal death under the acidosis induced by ischemic stroke." (PMID 38919602, 2024). "Our previous studies revealed the contribution of RIPK1 to ischemic stroke-induced neuronal and astrocytic cell necroptosis as well as its mechanisms, which are associated with autophagic-lysosomal pathway activation by RIPK1 in vivo and in vitro." (PMID 37055533, 2023). "Further studies using astrocyte-specific genetic disruption of RIPK1 function will be critical in establishing the mechanisms by which RIPK1 inhibition decreases the Hsp90 levels in ischemic stroke pathology." (PMID 37055533, 2023). "In previous studies, necroptosis was found to contribute to ischemic stroke by intervening in the RIPK1/RIPK3/MLKL signaling pathway in neurons and microglia." (PMID 38026442, 2023). "RIPK1 inhibitors exert protective effects in ischemic stroke, further revealing the contribution of necroptosis to ischemic stroke." (PMID 38026442, 2023). "Our previous study showed that pharmacological or genetic inhibition of RIPK1 protects against ischemic stroke-induced astrocyte injury." (PMID 37055533, 2023). "For example, it has been demonstrated that RIPK1 knockout mice exhibit greater resistance to ischemic stroke." (PMID 35054920, 2022). "RIPK1 was overexpressed in tissues of patients with ischemic stroke, atherosclerosis, and aortic aneurysm." (PMID 36249746, 2022). "RIPK1 is the first discovered molecule in the necroptosis pathway, it contributes to neuronal and astrocytic cell death in ischemic stroke via activating autophagic-lysosomal pathway." (PMID 35165268, 2022). "Insoluble RIPK1, RIPK3 and MLKL were detected in the infarct area of acute ischemic stroke mice, suggesting that necrotic apoptosis is associated with ischemic stroke." (PMID 36249746, 2022). "RhTrx‐1 provides neuroprotection in microglial inflammation induced by increased RIPK1 expression in ischaemic stroke." (PMID 32990414, 2020). "Administration of rhTrx‐1 provides neuroprotection in ischaemic stroke‐induced microglial neuroinflammation by inhibiting RIPK1 expression." (PMID 32990414, 2020). "Intracerebral hemorrhage, which can be seen in humans when ischemic strokes undergo hemorrhagic conversion, was significantly reduced in RIPK1 kinase dead mice and Ripk3−/− mice." (PMID 33142926, 2020). "Nec-1 treatment was able to protect against ischemic neuronal death by inhibiting RIPK1-mediated RIPK3/MLKL-dependent necroptosis in rat brains following ischemic stroke." (PMID 31440386, 2019). "Importantly, the simultaneous knockdown of Ripk1 and Nsf exerted neuroprotective effects on ischemic stroke by modulating the RIPK1/RIPK3/MLKL signaling pathway associated with necroptosis in neurons." (PMID 38919602, 2024). "Thus, CasRx-mediated knockdown of Ripk1 and Nsf holds promise as a neuroprotective strategy and provides a foundation for future gene therapy-based treatments for ischemic stroke." (PMID 38919602, 2024).